CYP17A1 (cytochrome P450 family 17 subfamily A member 1)
Diseases named in the same sentence as CYP17A1 in open-access papers (continued):
Sharing a sentence is not in itself a finding about the gene and the disease.
prostate carcinoma (continued). "Inhibition of CYP17A1 and CYP19A1 activities by curcuminoids indicate similar molecular entities or modified compounds based on core structures of curcuminoids could be explored as potential treatments for prostate cancer by targeting CYP17A1 and for breast cancer by targeting CYP19A1." (PMID 31533365, 2019). "Furthermore, several genetic association studies suggest that CYP17A1 plays an important role in different pathological conditions, such as visceral and subcutaneous fat accumulation, CAD, hypertension, prostate cancer, insulin resistance, and polycystic ovary syndrome." (PMID 29942286, 2018). "Abiraterone was caged by the [Ru(tpy)(dmbpy)] (dmbpy = 6,6′-dimethylbipyridine) center and its binding affinity for CYP17A1 and cytotoxicity against DU145 prostate cancer cell line were evaluated in the dark and after activation with light (λirr ≥ 395 nm)." (PMID 38672458, 2024). "Comparisons between primary prostate cancer and CRPC demonstrate that the transcription levels of these proteins are upregulated in CRPC and CYP17A1 protein is detectable in a subset of metastatic CRPC cases." (PMID 34630112, 2021). "Combining all the findings, it is possible to say that Morusflavone has the potential to form a stable interaction with the enzyme CYP17A1 that is similar to abiraterone, an FDA-approved inhibitor for prostate cancer." (PMID 34579444, 2021). "Hence, based on a previous study showing that CYP17A1 inhibition reduces DHEA production, we aimed to study whether the inhibition of CYP17A1 is effective at suppressing glioblastomas using abiraterone, which is a well-known chemotherapeutic drug for prostate cancer." (PMID 31527549, 2019). "The inhibition of CYP17A1 and CYP19A1 by curcuminoids provides a template for structure modification to produce effective and safe compounds that can target prostate cancer as well as breast cancer." (PMID 31533365, 2019). "To further substantiate these findings, we evaluated AR translocation in the human prostate cancer cell line PC346C, which naturally expresses ARwt and lacks CYP17A1 expression." (PMID 31017696, 2019). "Cytochrome P450 17A1 (CYP17A1), which converts pregnenolone to dehydroepiandrosterone (DHEA) in endocrine organs and the brain, is required for prostate cancer progression and acquired chemotherapeutic resistance." (PMID 28530704, 2017). "Cytochrome P450c17 (P450 17A1, CYP17A1) is a critical enzyme in the synthesis of androgens and is now a target enzyme for the treatment of prostate cancer." (PMID 26587646, 2015). "Thus, the current study supports the competent cytotoxic effect of CDRI-08 against androgen-independent prostate cancer cell lines, PC3, targeting the PI3K/Akt pathway, in combination with CYP17A1 inhibitor, AA, even in the presence of EGF and DHT." (PMID 40809182, 2025). "For instance, DHEA-S is a depot for local androgen synthesis in prostate cancer patients also after hormone therapy using 17a-hydroxylase-17,20-lyase (CYP17A1) inhibitors, and STS inhibitors demonstrated useful for the treatment of prostate cancer resistant to anti-androgen drugs." (PMID 37188267, 2023). "Ketoconazole is the first nonsteroidal CYP17A1 inhibitor used for prostate cancer treatment, with poor selectivity and mild androgen receptor agonist effects." (PMID 36838665, 2023). "The molecular structure of curcuminoids could be modified to generate better lead compounds with inhibitory effects on CYP17A1 and CYP19A1 for potential drugs against prostate cancer and breast cancer." (PMID 31533365, 2019). "However, the different binding mechanism of prostate cancer inhibitors of abiraterone and TOK-001 with CYP17A1 in terms of atomic-level structural characterization is still poorly elucidated." (PMID 26682016, 2015).
prostate carcinoma (continued). "The CYP17A1 enzyme (GeneID: 1586, 10q24.32, GRCh38 chr10:102,830,531-102,837,533, NCBI: NM_000102.4, NP_000093.1, OMIM: 609300) regulates sex steroid biosynthesis in humans through 17α-hydroxylase/17,20 lyase activities and is a target of the anti-prostate cancer drug abiraterone." (PMID 31533365, 2019).
Hypertension (40 papers, 2011 to 2025). The presence of chronic increased pressure in the systemic arterial system. "17α-hydroxylase deficiency, which is caused by a CYP17A1 gene mutation, is a rare type of congenital adrenocortical hyperplasia that mainly manifests as hypertension, hypokalaemia and sexual dysplasia." (PMID 37542252, 2023). "Similar to the human phenotype, the CYP17A1-deficient mice present the phenotype of metabolic syndrome with hypertension, increased serum glucose concentration, and presentation of central obesity and fatty liver." (PMID 37370070, 2023). "As previous genome-wide association study (GWAS) had confirmed, the polymorphisms of CYP17A1 were associated with hypertension and CAD, and successively be proved in Asian and Caucasian, also in our previous studies." (PMID 37370070, 2023). "The main clinical manifestations of CYP17A1 gene mutations are hypertension, hypokalaemia and sexual dysplasia." (PMID 37542252, 2023). "In this cross-sectional study of hypertensive molecular epidemiology, the association of the ATP2B1 and CYP17A1 SNPs, and their haplotypes, G × G and G × E interactions, with hypertension in the Maonan population was observed for the first time." (PMID 34722659, 2021). "Two large GWAS meta-analyses suggested that rs1004467 (P = 1.28 × 10−10) and rs3824755 (P = 1.21 × 10−6) in CYP17A1 were significantly associated with the risk of hypertension." (PMID 32977860, 2020). "Some genetic variants in CYP17A1 were associated with hypertension in different populations, such as rs11191548 which was found to be associated with both the She ethnic minority in China and the Chinese Han population." (PMID 32977860, 2020). "WES and Sanger sequencing identified the patient’s two variants of the CYP17A1 gene associated with hypokalemia, hypertension, and rhabdomyolysis." (PMID 31695722, 2019). "CYP17A1 deficiency caused by a mutation in the gene usually results severe hypertension and hypokalemia in males." (PMID 29338791, 2018). "Cytochrome P450 family 17 subfamily A member 1 (CYP17A1) gene encodes a key enzyme in the synthesis and metabolism of steroid hormones and has been associated with various factors, such as hypertension, insulin resistance, and polycystic ovary syndrome." (PMID 29942286, 2018). "CYP17A1 gene encodes a key enzyme in the metabolism of steroid which influences hypertension, VFA and SFA in Japanese women." (PMID 26485523, 2015). "The CYP17A1 polymorphism rs11191548 demonstrated a significant association with LVMI in patients with arterial hypertension and preserved LVEF." (PMID 26263970, 2015). "The present study aimed to investigate genetic associations of variants in or nearby the CYP17A1 gene with 24 h BP and left ventricular mass in treated high risk patients with arterial hypertension and associated cardiovascular organ damage." (PMID 26263970, 2015). "As conclusion, the CYP17A1 polymorphism rs11191548 has been identified as associated with LVMI in high risk patients with arterial hypertension and associated organ damage." (PMID 26263970, 2015). "Variants in the CYP17A1 gene, contained within a top selection candidate region identified in both Maduo and Tuo Tuo River populations, are associated with hypertension in European and Asian populations." (PMID 24642866, 2014). "In our diabetic subjects, rs1004467 in CYP17A1 had the most significant P value among the SNPs examined for hypertension; however, the association was only modest (P = 0.002; corrected P = 0.104)." (PMID 23133444, 2012). "17α-hydroxylase deficiency (17OHD), a rare autosomal recessive disease caused by CYP17A1 gene mutation, accounts for about 1% of all congenital adrenal hyperplasia and is characterized by hypertension, hypokalemia, and sexual infantilism." (PMID 21966534, 2011). "Studies have revealed that CYP17A1 gene variants may be linked to elevated blood pressure and a higher risk of hypertension." (PMID 37571339, 2023).
Hypertension (continued). "One hypothesis proposed that hypertension and hypokalemia caused by increased deoxycorticosterone levels due to CYP17A1 defects may play a dominant role in the pathogenesis of MMD, which requires further exploration." (PMID 36110215, 2022). "Therefore, the purpose of this research was to test the association of ATP2B1 (rs1401982 and rs17249754) and CYP17A1 (rs1004467 and rs11191548) SNPs, and their haplotypes, G × G and G × E interactions, with hypertension in the Maonan population." (PMID 34722659, 2021). "However, the evidence that showed the relationship of ATP2B1 and CYP17A1 with the hypertension risk from Maonan being one of China's ethnic minorities was still rare." (PMID 34722659, 2021). "Interestingly, there is a substantial literature supporting the potential of CYP17A1 as a causal gene for hypertension." (PMID 32984406, 2020). "Furthermore, rs1004467 in CYP17A1 is a common intronic variant that is associated with hypertension; it has been reported as a significant locus in the genome-wide meta-analysis and was verified in a Chinese Han cohort." (PMID 32977860, 2020). "The other two genetic loci of CYP21A2 rs2021783 and CYP17A1 rs4409766 were only found to be associated with blood pressure in a Chinese population, which indicated that these SNPs were genetic marker variants of hypertension in Chinese populations." (PMID 32977860, 2020). "In this article we have summarised evidence that common functional polymorphisms exist at the CYP11B1, CYP11B2 and CYP17A1 loci, and have hypothesised that each may predispose to hypertension." (PMID 28272372, 2017). "While CYP17A1 is associated with resting BP and hypertension in adults, whether the gene locus influences BP reactivity and whether it plays a role in BP regulation already in adolescence have not been studied." (PMID 25692033, 2015). "Given that CYP17A1 may enhance BP reactivity to mental stress, it may be an early genetic marker of hypertension risk." (PMID 25692033, 2015). "Against this background, we investigated associations between single nucleotide polymorphisms (SNPs) in or nearby the CYP17A1 gene with BP and left ventricular mass in patients with arterial hypertension and associated cardiovascular organ damage treated according to guidelines." (PMID 26263970, 2015). "Because we found a stronger association between CYP17A1 and AI in normotensive subjects, we hypothesized that arterial stiffness could be affected more by a certain genotype before the development of hypertension." (PMID 23133444, 2012). "The CYP17A1 p.R358X mutation has been reported in one girl of Korean descent with combined 17α-hydroxylase/17,20-lyase deficiency, who presented with primary amenorrhea, sexual infantilism, and hypertension." (PMID 21966534, 2011). "However, the genetic association between the ATP2B1 or CYP17A1 and hypertension was conflicting." (PMID 34722659, 2021). "The weak CYP17A1 inhibition detected in the in vitro experiments unlikely results in hypertension in patients." (PMID 39175536, 2024). "Several genes, including CYP17A1, CYP11B2, HSD11B1, CYP11B1, and NR3C2, which are implicated in the control of hypertension, regulate the synthesis of steroid hormones, such as glucocorticoids, mineralocorticoids, androgens, and estrogens." (PMID 37571339, 2023). "The ovaries play a role in the synthesis of estrogen and other hormones, and differences in the expression of ovarian steroidogenesis genes, such as CYP17A1 and CYP11B2, have been linked to a higher risk of hypertension." (PMID 37571339, 2023). "In the past 10 years, according to the results of GWAS scans, both ATP2B1 and CYP17A1 have correlation with BP and/or hypertension." (PMID 34722659, 2021). "In our study, we investigated the associations between rs4409766, rs1004467, and rs3824755 in CYP17A1 and rs2021783 in CYP21A2 and PE; several GWAS had identified these as the genetic variants associated with hypertension in China." (PMID 32977860, 2020).
Hypertension (continued). "Several genome-wide association studies have identified single-nucleotide polymorphisms (SNPs), such as rs4409766, rs1004467, and rs3824755 in CYP17A1 and rs2021783 in CYP21A2, as new hypertension susceptibility genetic variants in the Chinese population." (PMID 32977860, 2020). "The present study attempts to provide an analysis of epidemiological and genetic data towards the possible mechanism of the role of CYP17A1 in hypertension." (PMID 29338791, 2018). "In light of this, we propose that the differential response of variant CYP11B2, CYP11B1 and CYP17A1 genes to ACTH is an important determinant of blood pressure, tending to predispose individuals with an unfavourable genotype to hypertension." (PMID 28272372, 2017). "CYP17A1 has been identified as a gene locus of hypertension and resting blood pressure in several large-scale genome-wide and replication studies of adult European and Asian populations." (PMID 25692033, 2015). "Homozygous pathogenic variants in the CYP17A1 gene result in defective activity of the steroidogenic enzymes 17α-hydroxylase/17,20-lyase resulting in the clinical syndrome 17-OHD characterized by hypertension, hypokalemia, and disorders of sexual development." (PMID 39500362, 2025). "The majority of patients with combined 17α-hydroxylase/17,20-lyase deficiency due to severely inactivating CYP17A1 mutations first present with a lack of pubertal development and low renin hypertension." (PMID 34524979, 2021). "A smaller number of CYP17A1 missense variants are reported to exhibit partial impairment of 17α-hydroxylase/17,20-lyase activity, where hypertension is mild or absent and external genitalia appear ambiguous in 46,XY individuals." (PMID 34524979, 2021). "Similarly, three Turkish siblings with large-range deletions in CYP17A1 abolishing enzymatic activity presented with severe hypertension and primary amenorrhoea, but early onset adrenal insufficiency has not been reported by the authors." (PMID 34524979, 2021). "These novel findings provide important evidence that HDL and leptin maybe possibly mediate the process of CYP17A1 involved in hypertension." (PMID 29338791, 2018). "The SNP rs11191548 near CYP17A1 showed a significant association with hypertension, but the molecular mechanisms are not understood." (PMID 29338791, 2018). "In addition, we identified three SNPs in two novel genes (LOC729251 and TCEANC) and seven SNPs in five previously reported genes (FGF5, ATP2B1, CYP17A1, MTHFR and CASZ1) nominally associated with hypertension (Pmeta < 0.05)." (PMID 27480026, 2016). "One of the well-established gene loci of hypertension is CYP17A1." (PMID 25692033, 2015). "CYP17A1 is one of the well-established gene loci of adult hypertension." (PMID 25692033, 2015). "The results of the current study show that a well-established gene locus of hypertension in adults, CYP17A1, may play a role in increasing BP reactivity to stress during adolescence." (PMID 25692033, 2015). "Recently, some articles have reported that the CYP17A1 is related to hypertension, and one reason for how this gene leads to hypertension may be that genetic factors can influence the distribution of fat in body, and then lipid metabolism disorders can cause BP elevating." (PMID 34722659, 2021). "This study may not provide direct evidence that the expression of CYP17A1 influences hypertension because the lack of gene expression data, but our study demonstrated the associations of the SNP rs11191548 near CYP17A1 with HDL and leptin that contribute to hypertension." (PMID 29338791, 2018). "Moreover and for the first time, nominally significant parental genetic effects were found between the SNPs rs11191548 (CYP17A1) and rs17367504 (MTHFR) and child BP suggesting possible epigenetic mechanisms in the transmission of susceptibility to hypertension." (PMID 29045471, 2017).
Hypertension (continued). "Meanwhile, the haplotypes of CYP17A1 rs1004467A-rs11191548T, CYP17A1 rs1004467G-rs11191548C, and ATP2B1 rs1401982G-rs17249754A had a protective effect for hypertension, whereas the haplotype of ATP2B1 rs1401982A-rs17249754G revealed an increased susceptibility of disease (p < 0.001)." (PMID 34722659, 2021). "However, it does appear that phenotypic severity varies even in severely predicted CYP17A1 genotypes, as exemplified by a report of an adult prepubertal woman with an early truncation of the CYP17A1 protein (homozygous p.Y27X) who did not even develop hypertension." (PMID 34524979, 2021). "Meanwhile, GMDR analysis showed no statistical difference between the interaction of CYP17A1 and ATP2B1 on hypertension." (PMID 34722659, 2021).
breast cancer (35 papers, 1998 to 2025). A primary or metastatic malignant neoplasm involving the breast. "Supporting this association, a previous study identified a protein-truncating variant in CYP17A1 in three sisters with early-onset breast cancer." (PMID 41220582, 2025). "Some of the human disorders linked to CYP17A1 areprostate cancer, polycystic ovary syndrome, breast cancer, Cushing’ssyndrome, and glioblastoma." (PMID 37191389, 2023). "The enzyme contributes to the synthesis of estrogen precursors, and interventions targeting CYP17A1 have been explored to mitigate estrogen production and dampen the stimulatory effects on breast cancer cells." (PMID 40561159, 2025). "In breast cancer, abiraterone, targeting CYP17A1, was negatively correlated with STAT3 (r = −0.969) to the greatest extent compared with other compounds." (PMID 32486001, 2020). "Finally, in hormone-dependent prostate and breast cancers, CYP17A1 and CYP19A1 are targeted by inhibitors for cancer treatments." (PMID 31258835, 2019). "Combination with drugs that target CDK4/6, CYP17A1, or the PI3K/AKT/mTOR pathway, immunotherapies, or conventional treatments such as chemotherapy and radiotherapy may enhance the efficacy of breast cancer treatment." (PMID 39851328, 2025). "Here, in the present study, we identified the diosgenin to regulate the prolactin signaling pathway via the regulation of three genes i.e., STAT3, CYP17A1, and SRC which could avoid estrogen or progestogen receptor-mediated breast cancer progression." (PMID 36686654, 2022). "Whereas StAR and key steroidogenic enzyme genes evaluated (CYP11A1, HSD3B, CYP17A1, CYP19A1, and HSD17B) were altered to varying levels in these hormone responsive cancers, amplification of the StAR gene was correlated with poor overall survival of patients afflicted with breast cancer." (PMID 31060224, 2019).